GPC1 (glypican 1)
Diseases named in the same sentence as GPC1 in open-access papers (continued):
Sharing a sentence is not in itself a finding about the gene and the disease.
breast carcinoma (continued). "Both HER2 breast cancer cell lines, SKBR3 and BT-474, show similar relative gene expression levels of GPC1 and GPC4." (PMID 33742285, 2021). "In summary, we have found promising results in our study suggesting the prognostic power of GPC1, GPC3, GPC6 and potentially also GPC4 expression on the survival of breast cancer patients." (PMID 33742285, 2021). "In a study including 32 breast cancer samples, 75% of the patients were found to have increased levels of circulating exosomal glypican-1 (GPC1), a heparan sulfate proteoglycan that is overexpressed in breast cancer, compared to a control group." (PMID 33322643, 2020). "We optimized immunohistochemical staining of GPC1 on pancreatic (PANC-1) and breast cancer cells (MDA MB-231) obtained from tumor xenografts." (PMID 30800217, 2019). "Similar to GPC1, an increased expression of GPC6 has been reported in breast cancer." (PMID 33494442, 2021). "In the future, GPC1, GPC3, GPC4 and GPC6 might possibly serve as a basis for the medical treatment of breast cancer patients." (PMID 33742285, 2021). "Three exosomal membrane/surface proteins, glucose transporter 1 (GLUT-1), glypican 1 (GPC-1), and disintegrin and metalloproteinase domain-containing protein 10 (ADAM10), were identified as potential breast cancer biomarkers and validated with Western blotting and high-resolution flow cytometry." (PMID 32782317, 2020). "Thus, a new generation of bisphosphonate, zoledronate (zoledronic acid, Zometa), downregulates the expression levels of SDC1, SDC2, and GPC1 and upregulates the expression of SDC4 in breast cancer cells of low and high metastatic capability." (PMID 25140302, 2014). "As such, the upregulation of two cell-surface PGs, glypican-1 (GPC1) and syndecan-1 (SDC1), and of the extracellular sulfatase Sulf-2, have been described in malignant breast cancer tissues whilst the downregulation of some genes including SULF1 and HS3ST2 has also been reported." (PMID 23327652, 2013). "Glypicans display different activities in tumor development, while glypican-1 overexpression in tumor cells triggers mitogenic response, absence of glypican-3 expression in breast cancer cell lines inhibits mammary tumorigenesis." (PMID 23984412, 2013). "They found that GPC-1+ crExos strongly correlates with the PDAC rather than breast cancer." (PMID 36204449, 2022). "However, the same study showed that high levels of GPC1 on exosomes can be detected in breast cancer patients as well, suggesting that exosome GPC1 is not a tumor-specific marker." (PMID 32916840, 2020).
pancreatic ductal adenocarcinoma (33 papers, 2016 to 2026). An infiltrating adenocarcinoma that arises from the epithelial cells of the pancreas. "Literature also identified GPC1 as an independent risk factor in pancreatic ductal adenocarcinoma patients’ prognosis." (PMID 36895014, 2023). "Both mAbs recognized GPC1-expressing human tumor cell lines, including lung squamous cell carcinoma PC-10 and pancreatic ductal adenocarcinoma PK-45H, by flow cytometry." (PMID 42196164, 2026). "For example, Glypican 1 (GPC1) in pancreatic ductal adenocarcinoma (PDAC) cell lines and patient blood samples, and Glypican 3 (GPC3) in hepatocellular carcinoma (HCC) patient blood samples, follow the same pattern." (PMID 40285610, 2025). "This provides valuable information on the effectiveness of GPC1-based immunotherapeutic approaches for treating pancreatic ductal adenocarcinoma." (PMID 40282924, 2025). "For example, the circulating exosomal GPC1 level is typically increased in pancreatic ductal carcinoma (PDAC) and CRC patients." (PMID 38755598, 2024). "This study aimed to evaluate the potential of an anti-GPC1 monoclonal antibody (GPC1 mAb) labeled with 89Zr or 211At as a theranostic target in pancreatic ductal adenocarcinoma." (PMID 37827841, 2023). "GPC1 is a promising target for future applications for the precise diagnosis of pancreatic ductal adenocarcinoma and GPC1-targeted theranostics." (PMID 37827841, 2023). "For example, a study including 190 pancreatic ductal adenocarcinoma (PDAC) patients demonstrated that glypican-1 (GPC-1) was markedly higher in the patients’ serum exosomes than in healthy individuals." (PMID 36834471, 2023). "Other investigations have recently suggested that GPC1 expression is a prognostic biomarker for pancreatic ductal adenocarcinoma." (PMID 36158119, 2022). "It is worth mentioning that the development of exosome-containing GPC-1(GPC-1+ crExos) for pancreatic ductal adenocarcinoma (PDAC) is inspiring." (PMID 36204449, 2022). "The diagnostic performance and prognostic value of serum exosomal glypican 1 (GPC-1) in pancreatic ductal adenocarcinoma (PDAC) remain controversial." (PMID 36313694, 2022). "Circulating exosomes positive for GPC1 have been isolated from the serum of patients with pancreatic ductal adenocarcinoma." (PMID 33606708, 2021). "Recently, several scientific studies have been considering GPC1 a possible biomarker in pancreatic ductal adenocarcinoma and colorectal cancer through its detection in patients’ serum exosomes." (PMID 32180897, 2020). "Another important mechanism is about the promoter hypomethylation occurring in the GPC-1 gene in the pancreatic ductal adenocarcinoma, in which the GPC-1 mRNA and protein levels are found to be significantly increased." (PMID 31355137, 2019). "Glypican-1 (GPC1) is expressed in pancreatic ductal adenocarcinoma (PDAC) cells and adjacent stromal fibroblasts." (PMID 29721179, 2018). "Glypican-1 (GPC1) protein in exosomes was recently identified as a biomarker for the early detection of pancreatic ductal adenocarcinoma (PDAC)." (PMID 29245923, 2017). "In pancreatic ductal adenocarcinoma (PDAC), all 190 patient serum samples had higher GPC-1+ exosomes than healthy individuals, exhibiting a nearly perfect diagnostic value (~100 and ~100% in the receiver operating characteristic curve)." (PMID 31355137, 2019). "Research indicates that the lipid-anchored outer membrane protein GPC-1 is significantly overexpressed in plasma-derived exosomes from pancreatic ductal adenocarcinoma (PDAC) patients compared to healthy controls, confirming the potential utility of GPC-1 for early PDAC diagnosis." (PMID 39148736, 2024).
pancreatic ductal adenocarcinoma (continued). "Previous studies have demonstrated abnormal GPC1 expression in tumor tissues of pancreatic ductal adenocarcinoma and prostate cancer, but GPC1 was nearly absent in normal and adjacent tissues." (PMID 36158119, 2022). "Besides, GPC1 (glypican-1), a glycoprotein discovered in PSC exosomes, as a pivotal biomarker to distinguish PDAC (Pancreatic Ductal Adenocarcinoma), and as a tumor promoter shuttled among cells through exosomes." (PMID 29868251, 2018).
colorectal cancer (31 papers, 2017 to 2025). A primary or metastatic malignant neoplasm that affects the colon or rectum. "HMNs embedded with glypican-1 antibodies selectively bind tumor-derived exosomes, facilitating early colorectal cancer screening." (PMID 40136911, 2025). "HMNs functionalized with glypican-1 antibodies successfully captured tumor-derived exosomes, enabling early colorectal cancer detection." (PMID 40136911, 2025). "The GPC-1 protein has been identified as an exosomal marker in pancreatic, breast, and colorectal cancer." (PMID 38743146, 2024). "Glypican-1(GPC1) is specifically recognized for aiding in the detection of pancreatic, breast, and colorectal cancers." (PMID 38201485, 2023). "A mouse model of sporadic colorectal cancer showed that mouse adenocarcinoma tissues contained much higher levels of GPC1 than normal tissues." (PMID 36158119, 2022). "A previous study showed that plasma GPC1+ exosomes were significantly increased in colorectal cancer patients compared to healthy patients and reduced after surgery." (PMID 36158119, 2022). "GPC1 was suggested to be a biomarker of relapse of stage III colorectal cancer, and its level was correlated with poor survival." (PMID 32629890, 2020). "The percentage of plasma GPC-1+ exosomes significantly increased in colorectal cancer patients than those in healthy controls, and reduced after surgical removal." (PMID 31355137, 2019). "Many others since than have reported findings related to GPC1 detection in exosomes, not only in PC but also breast and colorectal cancer cases." (PMID 30671023, 2018). "To explore the specificity of GPC1, we analyzed expression of GPC1 in hepatocellular carcinoma (n = 40), cholangiocarcinoma (n = 40), gallbladder carcinoma (n = 40), colorectal carcinoma (n = 40), gastric carcinoma (n = 40), and prostate cancer (n = 40)." (PMID 30358133, 2018). "GPC1 promotes the proliferation and migration of colorectal cancer cells." (PMID 38168553, 2024). "Indeed, different studies have proved that glypican-1 (GPC-1) represents a diagnostic exosome marker for pancreatic, breast, and colorectal cancer (CRC)." (PMID 31935918, 2020). "Levels of glypican-1 and syndecan-2 are also increased in colorectal cancer." (PMID 31620357, 2019). "However, the expression of GPC-1 in colorectal cancer was controversial." (PMID 31355137, 2019). "Nonetheless, there are few systematic studies of GPC1 on the progression, prognosis, and immune response in COAD using bioinformatic approaches, especially in human colorectal cancer samples." (PMID 36158119, 2022). "Glypican-1+ (GPC1+) EVs were successfully isolated from tissues and plasma of Colorectal cancer (CRC)." (PMID 36407096, 2022). "In this study, we analyzed GPC family genes in colorectal cancer (CRC) and the possible mechanism of action of GPC1 in CRC." (PMID 35671267, 2022). "Furthermore, an increase in plasma glypican-1 positive exosomes and a reduction in plasma miR-96-5p and miR-149 expression were correlated to colorectal cancer diagnosis; whereas a normalization of these markers’ levels was achieved after successful colorectal cancer surgery." (PMID 29559954, 2018). "Heat shock protein 60 (a chaperonin involved in tumorigenesis), glypican-1, and the transmembrane protein CD147 are increasingly expressed in Colorectal Cancer, hence could be potential candidates for diagnosis." (PMID 36032679, 2022). "Right-sided colorectal cancers show that the expression of the HSPGs glypican-1,-3, and -6 and betaglycan are altered in non-metastatic tumors, whereas in metastatic tumors, only glypican-1 and SDC1 are modified." (PMID 30197623, 2018). "Serum GPC1 levels in PDAC were different from those in gallbladder carcinoma (P < 0.001), colorectal carcinoma (P < 0.001), gastric carcinoma (P < 0.001), and prostate cancer (P < 0.001), but not hepatocellular carcinoma (P = 0.395) and cholangiocarcinoma (P = 0.724)." (PMID 30358133, 2018).
colorectal cancer (continued). "Based on our results, the median serum GPC1 levels in colorectal carcinoma were not different from that of healthy controls (6.10, IQR: 4.87‐7.53 vs 5.78, IQR: 4.52‐7.37; P = 0.320)." (PMID 30358133, 2018). "The levels of serum GPC1 were not different among patients with HC and gallbladder carcinoma (P = 0.084) and colorectal carcinoma (P = 0.320)." (PMID 30358133, 2018). "We also find that GPC1 may be involved in EMT activation, invasion, and migration of colorectal cancer cells." (PMID 29254156, 2017). "We conclude that GPC1 can be a biomarker for relapse of stage III CRC and may be involved in EMT activation, invasion, and migration of colorectal cancer cells." (PMID 29254156, 2017). "Since crExos GPC1 levels are also elevated in patients with breast and colorectal cancers, this suggests that it would not be a good biomarker for screening for PDAC, but rather to monitor known disease or perhaps be used as an adjunct investigation in patients with suspected PDAC." (PMID 29721179, 2018). "The levels of serum GPC1 could distinguish PDAC from gallbladder carcinoma (P < 0.001), colorectal carcinoma (P < 0.001), gastric carcinoma (P < 0.001), and prostate cancer (P < 0.001), but could not differentiate PDAC from hepatocellular carcinoma (P = 0.395) and cholangiocarcinoma (P = 0.724)." (PMID 30358133, 2018). "However, recent studies indicate that plasma levels of GPC1+crExos are also elevated in stage II colorectal cancer, suggesting that GPC 1 + crExos may not be a specific marker for PC diagnosis." (PMID 38720811, 2024). "We found that serum levels of GPC1 can distinguish between PDAC and gallbladder carcinoma, colorectal carcinoma, gastric carcinoma, and prostate cancer, but could not differentiate PDAC from hepatocellular carcinoma and cholangiocarcinoma." (PMID 30358133, 2018).
prostate carcinoma (31 papers, 2013 to 2025). A carcinoma that arises from epithelial cells of the prostate gland. "This agrees with the observation in our study, where we saw increased migration of HS-5 cell aggregates following GPC-1 loss when treated with prostate cancer CCM." (PMID 33927256, 2021). "Further, treatment of human bone-derived prostate cancer cells (PC-3) with CCM from HS-5 cells exhibiting GPC-1 loss increased prostate cancer cell aggressiveness." (PMID 33927256, 2021). "Our finding that several markers of EMT and prostate cancer aggressiveness are elevated in PC-3 cells following treatment with CCM collected from HS-5 cells exhibiting GPC-1 loss further supports these observations." (PMID 33927256, 2021). "Clearly, detection of GPC-1 using MIL-38 has potential as a diagnostic approach for prostate cancer." (PMID 29672570, 2018). "Because its plasma, serum, and urine levels are elevated in patients with prostate carcinoma, GPC1 might serve as a reliable diagnostic marker for prostate cancer." (PMID 36158119, 2022). "The increase in paracrine activation of markers of cancer progressiveness in prostate cancer cells and the change their in cell morphology, following exposure to HS-5 cells in which GPC-1 was inhibited suggests that GPC-1 loss indirectly promotes an aggressive prostate cancer phenotype." (PMID 33927256, 2021). "Finally, GPC-1 was expressed in mouse tibia bone cells and present during bone loss induced by mouse prostate cancer cells in a murine prostate cancer bone model." (PMID 33927256, 2021). "Therefore, the loss of GPC-1 mimics the same HS-5 cell pro-inflammatory signature that is observed when they are exposed to prostate cancer CCM." (PMID 33927256, 2021). "We hypothesized that the loss of GPC-1 in HS-5 cells would support a more aggressive phenotype in the bone-metastasized prostate cancer cells." (PMID 33927256, 2021). "In pancreatic and prostate cancer, circulating GPC1 protein has been shown to be a prognosis biomarker." (PMID 39300946, 2024). "Further, GPC1 targeted positron emission tomography (PET) was recently tested with positive results as a novel diagnostic and therapeutic tool in glioblastoma and prostate cancer." (PMID 36944188, 2023). "The previous perception of GPC1 as a biomarker for prostate cancer has been challenged by recent findings that reveal its complex, paradoxical role in the regulation of prostate cancer cell proliferation and migration." (PMID 37775746, 2023). "Glypican-1 (GPC1), a cell surface proteoglycan with high expression in exosomes derived from prostate cancer cells, is one of the better studied markers that has also shown promise in PDAC." (PMID 36835649, 2023). "Some of these proteins with reduced expression after surgery are EMMPRIN, 60 kDa heat shock protein (HSP60), and glypican-1 (GPC1) for CRC, cytoskeleton-associated protein 4 (CKAP4) for PDAC, and prostate-specific membrane antigen (PSMA) for prostate cancer." (PMID 36831648, 2023). "Glypican-1 (GPC1) is a heparan sulfate proteoglycan that is highly expressed in human prostate cancer cell lines." (PMID 35740662, 2022). "GPC1-targeted NIR-PIT significantly reduced the viability of GPC1-expressing human prostate cancer cells in vitro." (PMID 35740662, 2022). "GPC-1-dependent phenotypic changes were similar to that seen in wild type HS-5 cells when exposed to CCM from prostate cancer cells." (PMID 33927256, 2021). "Together, these data suggest that GPC-1 indirectly regulates prostate cancer phenotype, migratory behavior and gene expression via the induction of activated fibroblasts in the bone microenvironment." (PMID 33927256, 2021). "To investigate the effect of GPC-1 inhibition in HS-5 cells on prostate cancer cell morphology, we exposed PC-3 cells with CCM isolated from HS-5 cells." (PMID 33927256, 2021). "Regardless of the mechanisms involved, our study is the first to report that GPC-1 modulates cell aggregation in BSCs after their exposure to prostate cancer CCM." (PMID 33927256, 2021).